CD4 (CD4 molecule)
Diseases named in the same sentence as CD4 in open-access papers (continued):
Sharing a sentence is not in itself a finding about the gene and the disease.
melanoma (continued). "Consistent with previous analyses, we found that inhibition of SPHK1 activity significantly diminished the levels of CD4+CD25+FoxP3+ regulatory T cells (Tregs) and Gr-1+CD11b+ myeloid-derived suppressor cells (MDSCs) in melanoma." (PMID 36050478, 2022). "A spate of recent studies have used diverse in vivo models to demonstrate a functional role for NKG7 in CD4+ T cells (visceral leishmaniasis), CD8+ T cells (malaria), NK cells (melanoma) and in CD8+ T cell driven anti-tumor immunity." (PMID 35874669, 2022). "The BF multiplex IHC staining was performed using different combinations of six immune-cell markers—CD3, CD4, CD8, CD20, CD68 and CD163—and the melanoma cell marker SOX10." (PMID 35954345, 2022). "We identified a total of 67,917 genes in malignant CD4, 63,038 genes in malignant CD8 and 56,827 genes in malignant Treg from five tissues (breast, lung, colorectal, head and neck and melanoma)." (PMID 36232369, 2022). "MHC class I-restricted CD4+ TCR-Ts were found to synthesize Th1 cytokines and exhibit cytolytic effector functions in a human melanoma model." (PMID 35928827, 2022). "In melanoma, the TRAIL-TRAIL receptor axis can mediate cytotoxic activity by CD4 T cells against tumour cells." (PMID 35572552, 2022). "In an alternative comparison, among the FOXP3+CD4+ Tregs, the percentage of GATA3+ cells was elevated in invasive melanoma compared with in situ melanoma." (PMID 36107619, 2022). "Significantly fewer γδ T cells, CD4+, CD8+ T or CD11b+ cells were in the melanoma–fibroblast bicellular spheroids than those in the unicellular spheroids." (PMID 35731974, 2022). "In agreement with this possibility, we observed higher frequencies of CD4+, and to a lesser extent CD8+, CD39+PD‐1+ MAIT cells in melanoma tumors from mucosal sites (nasopharynx and jejunum)." (PMID 35028137, 2022). "A recent clinical trial conducted in patients with melanoma showed that vaccination with a long 30-mer peptide from NY-ESO-1, Montanide, and CpG-B is safe and well-tolerated and leads to CD4+ and CD8+ antigen-specific T cell responses." (PMID 35651800, 2022). "In melanoma patients, the repertoire of CD8-positive T cells in the peripheral blood was more restricted than that of CD4-positive T cells." (PMID 36361781, 2022). "While anti-CSF-1R treatments demonstrated limited efficacy alone, anti-CSF1R treatment in combination with anti-PD-1 therapy significantly decreased M2 TAMs while increasing the number of CD4+ and CD8+ TILs in murine models of melanoma." (PMID 35345849, 2022). "Our results showed that both CD4 and CD8 T cell subsets were equally capable of inhibiting melanoma-conditioned macrophage-derived CCL2, VEGF, and IL-6 in a contact-independent manner." (PMID 35265066, 2022). "Upon lung infiltration, IVneg CD4+ and CD8+ T cells significantly upregulated TNFα expression in WT and B2m-/- B16 melanoma-challenged mice compared to the controls." (PMID 36733396, 2022). "While ipilimumab and tremelimumab increased intra-tumoral CD4+ and CD8+ effector T-cells in these solid malignancies, intra-tumoral FOXP3+ T-cells were also increased in melanoma samples." (PMID 35326731, 2022). "Compared with human tonsil, germinal centers from human melanoma generally contained reduced numbers of both BCL6+CD20+ B cells and BCL6+CD4+ T cells." (PMID 34248957, 2021). "Treating immune-competent mice bearing mouse melanoma with PS-acet.-STAT3 peptide inhibited STAT3 in tumor-infiltrating T cells, downregulating tumor-infiltrating CD4+ T regulatory cells while activating CD8+ T effector cells." (PMID 33491667, 2021). "Evidence has shown that CD4+ and CD8+ memory T cell subsets, as well as NK cell subsets, correlated with a clinical response to immunotherapy in patients with melanoma." (PMID 34054849, 2021).
melanoma (continued). "Increasing knowledge shows the importance to elicit also CD4 T cells, in particular in cases where tumor cells downregulate MHC class I and mainly express MHC class II molecules, like in melanoma, lung cancer, breast and osteosarcomas." (PMID 34064410, 2021). "We further showed that CIRT was able to increase the abundance of CD4+ and CD8+ T lymphocytes in melanoma-bearing mice, increased the population of macrophages and natural killer cells and reduced the percentage of Treg." (PMID 34732697, 2021). "In patients with melanoma treated with PD-1 inhibitors, a higher frequency of circulating CD8+ TEM cells and lower frequency of CD4+ TEM cells and naïve CD8+ T cells at baseline were observed in responders." (PMID 34502325, 2021). "In syngeneic mouse tumor models, PDI-1 inhibited the growth of hPD-L1-expressing melanoma and NSCLC by increasing the abundance of effector CD8+ T cells and decreasing that of inhibitory FoxP3 CD4+ Tregs." (PMID 34054817, 2021). "Programmed cell death-1 (PD-1) expression on CD4+ and CD8+ TILs is increased during cutaneous metastasis originating from melanoma and this increase leads to declined production of IFN-γ in these cells." (PMID 32902664, 2021). "We recently expanded this knowledge by characterizing CD4 T cells with cytolytic capacities in melanoma patients using innovative nanobiosensors and direct sorting of TAA-specific CD4 T cells using combinatorial peptide-MHC class II multimers." (PMID 34064410, 2021). "Normal CD4 and CD8 T cell development is observed in Batf−/− mice, supporting the use of this mixed BMC model to study CD8 T cells’ differentiation in melanoma." (PMID 33809259, 2021). "As determined by mass cytometry of melanoma tissues using a panel of 43 markers, CD8+/CD4+EOMES+CD69+CD45RO+ effector memory T cells were significantly more abundant in responders of combined immunotherapy compared with non-responders." (PMID 34360781, 2021). "In melanoma patients, we revealed that tumors exhibiting high CCL5 are less hypoxic, and displayed high NK, CD3+, CD4+ and CD8+ T cell markers than those having low CCL5." (PMID 34155342, 2021). "Vaccination with DEXsOVA-CTLA-4 increased the migration of CD4+ and CD8+ T cells to the tumor site and elevated the ratio of CTLs/Tregs in the microenvironment of B16 melanoma tumor model after 12 days." (PMID 34335627, 2021). "In melanoma-bearing mice, treatment with IDO-siRNA using mannosed liposomes has decreased apoptosis in CD8 and CD4 T-cells." (PMID 33692796, 2021). "Spontaneous regression is thought to result from an effective immune response with CD4+ and CD8+ T-cells directed against melanoma cells." (PMID 34607999, 2021). "Although both CD4+ and CD8+ T cells are identified on biopsy of macules, CD4+ T cells dominate the infiltrates reported in melanoma patients receiving ipilimumab." (PMID 35154081, 2021). "In those studies, IL12/15/18-activated NK cells exhibited a stable and persistent enhanced ability to control B16 melanoma cells in vivo, in a mechanism dependent on IL2 produced by CD4+ T cells." (PMID 34187852, 2021). "In a BRAF‐mutated melanoma, this T‐cell response could be amplified, by broadening the TCR repertoire at baseline (BRAF/MEK inhibitors) and by subsequently increasing the number of proliferating CD4+ T cells (checkpoint inhibitors), thus improving the likelihood of a positive ICI therapy response." (PMID 33449393, 2021). "Vaccination induced strong multifunctional neoantigen-specific CD4+ and CD8+ T-cell responses in melanoma patients after surgical resection." (PMID 33503926, 2021). "Of the proteins that were measured across all three tumor datasets, we observed that CD4, CD45RO, GZMB, Ki67, PTEN, Bcl-2, CD19/20, and Pan-CK are positively correlated with CD8 in GBM and in at least one melanoma treatment arm." (PMID 34188042, 2021). "Enhanced expression of LAG-3 has been detected on CD4+ and CD8+ T cells infiltrating into metastatic lymph nodes of patients suffering from melanoma." (PMID 32902664, 2021).
melanoma (continued). "Second, we observed that naive B cells, Treg cells, memory resting CD4 T cells, memory B cells, activated mast cells, and resting NK cells were upregulated in low-TMB populations, which could shed light into the immune mechanism underlying the development of melanoma." (PMID 33758620, 2021). "In patients with advanced melanoma, this treatment showed a strong CD8 but a weak CD4 T cell response, probably due to the migration of the latter to the tumor site." (PMID 34064410, 2021). "For example, melanoma patients exhibited increased tumor infiltration by CD3+ CD8+ and CD3+ CD4+ and decreased CD4+ FOXP3+ Tregs after treatment with ECT plus bleomycin." (PMID 34358144, 2021). "CTLA-4 is also a direct target gene of Wnt/β-Catenin in melanoma: it increases the production of IFN-γ by CD8+ and CD4+ TILs." (PMID 34830209, 2021). "In a more recently published systematic review, a favorable prognostic role of the CD3+, CD4+, CD8+, FOXP3+, and CD20+ TILs on the overall survival of melanoma patients was confirmed." (PMID 33854972, 2021). "For example, six proteins, including CD4 and CD45RO, are positive predictors of CD8 in both GBM and at least one of the two melanoma cohorts." (PMID 34188042, 2021). "In the present study, we showed that anti-CD4 treatment, in combination with ACT and CTXpre, enhanced anti-melanoma efficacy by enriching IL-18Rαhi CD8+ T cells." (PMID 34493727, 2021). "The DURAClone IM T cell subsets tube and MoT assay agreed in 81/83 cases (98%) when classifying patients as CD4+ TEM≥16% or CD4+ TEM<16% Furthermore, the MoT test performed well in predicting hepatitis in a cohort of 16 Stage IV melanoma patients." (PMID 34868015, 2021). "In univariate analysis of immunohistochemical features, FOXP3, CD4, CD8, PD-1, and Melanoma Institute of Australia (MIA) grading TILs (grade, density, and distribution) were correlated with survival." (PMID 33916279, 2021). "TIGIT expression is also enhanced on CD4+ and CD8+ T cells that infiltrated melanoma tumors in mice afflicted by B16F10 melanoma tumors." (PMID 32902664, 2021). "Consistently, combination therapy of anti–CTLA-4 and anti–PDL-1 mAbs plus an anticancer vaccine resulted in a significant increase in IFN-γ production by both CD4+ and CD8+ cells, which correlated with higher rates of melanoma tumor rejection." (PMID 33777008, 2021). "In our study, we found that a high level of activated memory CD4+ T cells and a low level of resting memory CD4+ T cells were correlated with a higher response rate and prolonged survival of ICI-treated melanoma patients." (PMID 34220837, 2021). "Immunohistochemical quantitative analysis of TILs, including expression of CD4, CD8, FOXP3, PD-1, and PD-L1, on melanoma cells was performed." (PMID 33916279, 2021). "Our results also revealed increased frequencies of the CD25+ cells for both CD4+ and CD4-CD8- T cell subsets in canine melanoma patients compared to healthy dog controls." (PMID 34926643, 2021). "Other groups have identified CD279 (PD-1) expression in CD8+ T cells as a marker of clinical response after αPD-1/αCTLA-4 treatment in patients with melanoma; therefore, our panel also enables quantification of CD45+ CD3+ CD4- CD8+ CD279+ events." (PMID 34868015, 2021). "In this study, an examination of DC-vaccinated mice showed that the G-exo-stimulated DC vaccine significantly induced tumor antigen-specific multifunctional CD4+ and CD8+ T cells in melanoma tumor-bearing mice." (PMID 33228229, 2020). "All phenotypic and functional markers of T cells—CD3E, CD4, CD8B, FOXP3, GZMB, PRF1 and TBX21—were expressed at higher levels in melanoma patients with high ETV7 expression." (PMID 33424867, 2020). "The expansion of CD4+ and CD8+ T cells expressing cytotoxic molecules were also observed in melanoma patients treated with two checkpoint blockers." (PMID 32226027, 2020).
melanoma (continued). "In a clinical trial, vaccination of melanoma patients with TAA‐loaded autologous pDCs drove antigen‐specific CD8+ and CD4+ T‐cell responses and improved OS49 showing the reversibility of pDCs subversion by tumor cells." (PMID 33282290, 2020). "Concurrently, the expression of IFN-γ and TNF-α, major cytotoxic effector cytokines, in CD4+ and CD8+ T cells was higher in B16 melanoma of Lsp1 KO mice than in control mice." (PMID 33020243, 2020). "Treg cells can recognize specific melanoma markers gp100 and TRP-1, produce IL-10 and inhibit anti-tumor response of T lymphocytes CD4+CD25−." (PMID 33287312, 2020). "When M2-TAMs was depleted, there was a marked increase in the numbers of CD4+ and CD8+ TILs in melanomas." (PMID 32756500, 2020). "Nevertheless, a study which examined only melanoma metastases within the SLN and enumerated intratumoral lymphocytes by visual counting, higher counts of CD4+ TIL were significantly correlated to increased OS and RFS." (PMID 33013886, 2020). "In contrast to CD4+ T cell activation, calcium EP was shown to increase the CD8+ T cell activation potential of melanoma conditioned BMDMs." (PMID 33244152, 2020). "We and others established the existence of CD4 Th1 cell specific for different TERT epitopes in several cancers including leukemia, lung, colon, melanoma, renal, and liver cancers." (PMID 32630460, 2020). "They showed that the nanoplatforms were rapidly uptaken by DCs and induced a strong CD4+ (Helper) T-cell and CD8+ (cytotoxic) T cell-mediated immune response, resulting in delayed tumor growth in B16F10 melanoma tumor bearing mice." (PMID 33409265, 2020). "Based on clinical outcomes observed in melanoma patients treated with TILs, the CD8+/CD4+ ratio and the number of CD8+CD27+ T cells infused in these patients correlated with their response to treatment." (PMID 33208551, 2020). "Knowledge of the mechanisms through which T helper subsets influence tumor development has been largely obtained from in vivo murine models where both CD4+ TH1 and TH2 cells have been shown to eliminate B16 melanomas." (PMID 33013886, 2020). "They found distinct clonal expansions of CD4+ and CD8+ T cells in the melanoma and CSF, with considerable overlap between the T cell receptor repertoire in the tumor and the first, but not second CSF sample." (PMID 33362680, 2020). "In two types of patients with cancer, melanoma and NSCLC, those whose tumors exhibited increased inflammatory gene transcripts with high circulating CD4+ and CD8+ central memory T cell (Tcm) to effector T cell ratios had longer PFS." (PMID 33268350, 2020). "Higher proportions of NK cells, CD4+ and CD4+ CD8α+ T cells, and CD21− B cells among B cells are found in young melanoma-bearing piglets, consistent with the immune-mediated spontaneous regression in the MeLiM model." (PMID 32180771, 2020). "Although we did not formally prove that protection is dependent on CD4+ and CD8+ Trm, we have previously reported that protection using the B16-F10 melanoma model is highly dependent on CD8+ T cells, and in a lesser extent also on CD4+ T cells." (PMID 33240271, 2020). "NO inhibits antigen presentation from DCs to CD4+ T cells in the presence of MDSCs in melanoma cells, and nitrated STAT1 can be found in melanoma specimens." (PMID 33255891, 2020). "To address the individual contributions of different memory T cell populations for protection against melanoma growth, we eliminated the circulating CD8+ or CD4+ T cells injecting i.p. eight doses of anti-CD8 or anti-CD4 mAbs." (PMID 33240271, 2020). "Both subpopulations of effector T lymphocytes, CD4+T helper cells (p < 0.001) and CD8+CTLs (p < 0.001), were significantly reduced in the melanomas of B16F10+MSC14d-treated mice compared to B16F10+PBS14d-treated animals." (PMID 32695181, 2020). "Using multicolor IHC, we analyzed the distribution of CD4+/CD8+ T cells and B cells in whole tumor tissue slices from a B16F0 melanoma model." (PMID 32457825, 2020).
melanoma (continued). "The higher proportions of NK cells, CD4+ and DP T cells and CD21− B cells among B cells in young melanoma-bearing piglets compared to healthy age matched pigs is in accordance with the mounting of an immune response against melanoma." (PMID 32180771, 2020). "A significantly higher number of CD4+T helper (p < 0.05) and CD8+CTLs (p < 0.05) were present in the tumors of B16F10+MSC1d-treated mice than in melanomas of B16F10+PBS1d-treated animals." (PMID 32695181, 2020). "Methylation analysis in melanoma cell lines and isolated leukocyte subsets (monocytes, B cells, CD8+ T cells, CD4+ T cells, and regulatory T cells) revealed striking differences in methylation patterns." (PMID 32861198, 2020). "We analyzed melanocyte and melanoma cell lines as well as immune cells, including monocytes, CD8+ and CD4+ T cells, B cells, and granulocytes." (PMID 31747929, 2019). "Immune profiling revealed a higher density of melanoma-infiltrating CD8+ T cells at baseline and a higher frequency of blood-circulating CD8+ and CD4+ T cells in responder patients with a favorable gut microbiome." (PMID 31557787, 2019). "Muranski and coworkers created a transgenic mouse expressing MHC class II-restricted T cell receptor, in which CD4+ T cells recognize tyrosinase-related protein 1 (TRP-1), an antigen present both in normal melanocytes and B16 melanoma cells." (PMID 30800130, 2019). "The combination hypothesis has been evaluated by in vivo experiments in a murine melanoma model in which the antitumor activity of 4-1BB/CD137 was significantly improved when given in combination with an anti-CD4 mAb that depleted Tregs as well as other CD4+ cells." (PMID 31801624, 2019). "Together, degrees of repertoire restrictions in CD4+ and CD8+ blood T cells showed positive correlations with each other in melanoma patients both before and after CTLA4 blockade." (PMID 31275310, 2019). "The timing of the melanoma growth control suggested the generation of an anti-cancer effector T cell response, therefore we analyzed CD8+ and CD4+ T cells present in the tumor-draining iLN (tdLN) and the grafted B16-OVA tumor 3 days after cDC1 administration." (PMID 30961656, 2019). "Following excision of primary B16 melanoma tumors, mice were vaccinated with optTRP1455 peptide and also given TGF-β blockade to reverse the tumor and regulatory CD4+ (Treg) cell TGF-β-mediated suppression of CD8+ T cells." (PMID 31379821, 2019). "In contrast, in melanoma patients, numbers of restricted TCR Vβ-gene families showed statistically significant positive correlations between CD4+ and CD8+ T cells (p = 0.0026)." (PMID 31275310, 2019). "In this respect, based on the identified correlations, we characterized the production of KYN, 3-HK, and KYNA in vitro using melanoma-derived BRAF wild type (wt) and BRAF V600E mutant cell lines cultured with primary CD4+ CD25− T-cells." (PMID 31434983, 2019). "Here we already combined the melanoma specific gp100 HLA-DR4 and HLA-A2 restricted epitopes for activation of both CD4+ and CD8+ gp100 specific T cells." (PMID 31534520, 2019). "According to D’Amico, DKK1 activates Myeloid-derived suppressor cell (MDSC), a suppressor of tumor immunology, to indirectly reduce accumulation of CD4+ and CD8+ TILs in Lewis lung carcinoma, pancreatic cancer as well as B16 melanoma." (PMID 31830954, 2019). "Melanoma growth is accelerated in the P2X7 null host, in correlation with a significant decrease in the CD8+ and CD4+ effector T cells (Teff, CD4+, CD25−) infiltrate." (PMID 30655604, 2019). "We demonstrate that combination of RTx with HHP vaccine also fosters infiltration of CD4+ and CD8+ T cells as well as that of NK cells and γδT cells into B16-F10 melanomas." (PMID 31555582, 2019). "Combined with CD4/CD8 separation, our analyses now revealed that CD4+ and CD8+ T-cell repertoires in circulation of patients with advanced melanoma were restricted, with T-cell clones that were diversified in terms of Vβ-gene family and CDR3 length." (PMID 31275310, 2019).